MMP9 (matrix metallopeptidase 9)
Diseases named in the same sentence as MMP9 in open-access papers (continued):
Sharing a sentence is not in itself a finding about the gene and the disease.
bladder cancer (continued). "The expression of MMP2 and MMP9 was significantly reduced after FXR overexpression, which may inhibit invasion in human bladder cancer T24 cell." (PMID 35563650, 2022). "The expression levels of MMP-2 and MMP-9 in bladder cancer cells transfected with Nucb2 shRNA was lowered, indicating that Nucb2 may affect cancer migration and invasion through the MMP-2 and MMP-9 signaling pathways." (PMID 34073612, 2021). "Recent studies have found that HSPA6 can enhance the inhibitory effect of garlic extract on the proliferation, migration, and invasion of bladder cancer cells by enhancing the ATM-CHK2-Cdc25C-p21 WAF1-Cdc2 cascade response and MAPK and Akt phosphorylation and inhibiting MMP-9 expression." (PMID 34489426, 2021). "IL‐20 could also induce bladder cancer cell migration by activating the ERK‐mediated NF‐κB pathway, and promoting MMP‐9 production subsequently." (PMID 33900049, 2021). "Additionally, the treatment of bladder cancer cells with MSSV suppressed migratory and invasive potential via the transcription factor-mediated expression of matrix metalloproteinase 9 (MMP-9)." (PMID 33430488, 2021). "Immunohistochemistry (n = 55) was used to detect Chemokine (C-X-C motif) ligand 8 (CXCL8), CD163 (a TAM marker), Matrixmetalloproteinase-9 (MMP-9), vascular endothelial growth factor (VEGF), and E-cadherin in cancerous and adjacent tissues of bladder cancer patients." (PMID 32201645, 2020). "Together, this study identified four prognostic hub immune-related genes, including MMP9, IGF1, CXCL12 and PGF, which might play a vital role in bladder cancer development." (PMID 32675942, 2020). "Moreover, in bladder carcinoma cells, maspin modulated HDAC1 target genes, including cyclin D1, p21, MMP9, and vimentin." (PMID 31861435, 2019). "The expression of seven of the 10 bladder cancer -associated diagnostic signature (MMP9, MMP10, PAI1, CA9, APOE, SDC1, and ANG) showed a positive association with bladder cancer diagnosis, while IL8 and A1AT showed a negative correlation with cancer diagnosis." (PMID 31905599, 2019). "In urinary bladder cancer cell lines, fucoidan (F. vesiculosus) inhibited MMP-9 expression without affecting AKT protein levels in vitro." (PMID 30621045, 2019). "Our results demonstrated that MMP9 may be a universal downstream target of OPN in both colon and bladder cancer progression." (PMID 29851214, 2018). "In addition, MMP-9 and MMP-9 dimer were identified as multivariable predictors for differentiating prostate from bladder cancer (P < 0.001)." (PMID 30197761, 2018). "Other studies showed that the over-expression of circHIPK3 induced efficiently interaction with miR-558 and then down-regulated the expression of HPSE and its downstream targeted MMP-9 and VEGF to attenuate the promoting effect of miR-558 on bladder cancer cell migration, invasion, and angiogenesis." (PMID 30134837, 2018). "In particular, Davies and coworkers reported that the expression of MMP-9 was significantly higher in the tumor tissues of bladder cancer patients as compared to non-cancerous tissues from the same patients." (PMID 30034317, 2018). "Studies have shown that bladder cancer invasion may be promoted by the p38 MAPK pathway through the regulation of the downstream MAPKAPK2 so as to regulate MMP-2 and MMP-9 activity." (PMID 29794990, 2018). "In conclusion, this study demonstrated that flaccidoxide-13-acetate inhibits the migration and invasion of T24 and RT4 bladder cancer cells through the down-regulation of MMP-2 and MMP-9 expressions, and the process is controlled by the FAK/PI3K/AKT/mTOR pathway." (PMID 29280977, 2017). "We further demonstrated, using bladder cancer lines, that ZKSCAN3 knockdown resulted in significant reduction of cell viability, colony formation, cell migration, cell invasion, and the expression of MMP-2/MMP-9, as well as significant induction of apoptosis." (PMID 27447553, 2016).
bladder cancer (continued). "On the other hand, we also observed that miR-199a-5p could directly target the 3′UTR of CCR7 and regulate the expression of MMP-9 and EMT-related proteins like vimentin and E-cadherin, eventually suppress the progression of bladder cancer." (PMID 27814720, 2016). "In the current study, ELK1 silencing in AR-positive bladder cancer lines cultured with androgen resulted in significant decreases in cell migration and invasion as well as the expression and enzymatic activity of MMP-2/MMP-9." (PMID 26342199, 2015). "When comparing the level of MMP9 in schistosomal and non-schistosomal bladder cancer groups; there was also a significant elevation of MMP9 in non-schistosomal bladder cancer group when compared to the schistosomal bladder cancer group." (PMID 25135219, 2014). "So the aim of the present study was to evaluate the urinary levels of MMP3 and MMP9 in different stages of schistosomal and non-schistosomal bladder cancer in Egyptian patients." (PMID 25135219, 2014). "In the current study, urinary MMP9 was not increased in superficial stages of both types of bladder cancer either related or unrelated to schistosoma infection." (PMID 25135219, 2014). "In addition, increased VEGF and MMP-9 expression correlated with EMT changes and poor prognosis of bladder cancer." (PMID 24886404, 2014). "Taken together, cantharidin was suggested to present antimetastatic potential via suppressing the levels of MMP-2 and MMP-9 expression that might be mediated by targeting the p38 and JNK1/2 MAPKs pathway in TSGH-8301 human bladder cancer cells." (PMID 23431332, 2013). "In the current study, MMP-9/NGAL enzyme activity was detected in about 60% of the urine specimens of the bladder cancer patients but not in any of the urine control healthy cases (p = 0.001)." (PMID 23672427, 2013). "As we have revealed the down-regulation of ROCK1, MMP2 and MMP9 in bladder cancer tissues by IHC, we wanted to know whether knocking down miR-124-3p could result in the up-regulation of ROCK1, MMP2 and MMP9." (PMID 24180482, 2013). "The purpose of this study was to investigate whether the expression of MMP-9, MMP-2 and its specific inhibitors, are expressed in a reproducible, specific pattern and if the profiles are related to prognosis in Bladder Cancer (BC)." (PMID 22695075, 2012). "A recent report indicated that MAPKAPK2 could mediate p38 mitogen-activated protein kinase (MAPK) activation to drive invasion of bladder cancer by inducing the expression of MMP-2 and MMP-9." (PMID 22140479, 2011). "Nonetheless, similar inhibitory effects of dutasteride on the cell growth, as well as the expression of oncogenic proteins including β-catenin, Bcl-2, MMP2, MMP9, NF-κB, and p21, were seen in AR-negative bladder cancer lines, suggesting the involvement of the non-AR pathway." (PMID 40486871, 2025). "For example, in bladder cancer cells, Capsaicin reduces the deacetylase of SIRT1, enhances the acetylation of cortactin and β-catenin, thereby reducing the activation of MMP-2 and MMP-9, and ultimately leads to the migration disturbance of bladder cancer cells." (PMID 40007993, 2025). "We found that the protein level of MMP9 was unchanged, while TRIM9 overexpression facilitated MMP2 production in Biu-87/T24 cells, and blockade of Smad2/3 signaling suppressed MMP2 expression, indicating that Smad2/3 mediated downstream MMP2 production in bladder cancer cells." (PMID 37249822, 2023).
bladder cancer (continued). "Consistent with previous studies, we also found that AnxA2 knockdown significantly inhibited bladder cancer cell proliferation, migration, and invasion, along with remarkably decreased expression of proangiogenic proteins such as PDGF-BB, ANGPT1, ANGPT2, Tie-2, bFGF, GRO, IL-6, IL-8, and MMP-9." (PMID 36428758, 2022). "Furthermore, MMP-9 rs3918242 was not related to the incidence of certain cancer types, like bladder cancer, CRC, and esophageal cancer." (PMID 35574300, 2022). "In addition, the downregulation of AnxA2 cells significantly inhibited the proliferation, migration, and invasion in bladder cancer along with the reduction in proangiogenic factors and cytokines such as PDGF-BB, ANGPT1, ANGPT2, Tie-2, bFGF, GRO, IL-6, IL-8, and MMP-9." (PMID 36428758, 2022). "Furthermore, CXCR2 stimulation could promote bladder cancer cell migration and invasion by activating the PI3K/AKT-induced upregulation of MMP2/MMP9." (PMID 31681401, 2019). "However, 1,25D3 did not affect the expression of E-cadherin, MMP-2 nor MMP-9 in bladder cancer cell lines (data not shown)." (PMID 28947955, 2017). "This may explain the increase in urinary levels of MMP3 rather than MMP9 in the early stages of both schistosomal and non schistosomal bladder cancer patients." (PMID 25135219, 2014). "Furthermore, we demonstrated miR-124-3p could inhibit bladder cancer cell epithelial mesenchymal transfer, and regulated the expression of c-Met, MMP2, MMP9." (PMID 24180482, 2013). "In addition, we performed Immunohistochemical staining to assess the expression of MMP2 and MMP9 in human bladder cancer tissues, comparing with the paired non-tumor tissues." (PMID 24180482, 2013). "In addition, MMP9, MMP13, and TIMP1 are expressed in many bladder cancers and may mediate tumor invasiveness through extracellular matrix regulation." (PMID 23209855, 2012). "Moreover, the studies confirmed that cytokines might increase MMP-2 and MMP-9 expression and activation of NF-κB and AP-1, which regulate the MMP-9 promoter in muscle-invasive and non-muscle-invasive bladder cancer." (PMID 33923108, 2021). "These proteins may not effect proangiogenic pathways in bladder cancer; they can however interact with IL-1α, IL-8, VEGF (vascular-endothelial growth factor), and MMP-9 (matrix metalloproteinase-9) to enhance tumorigenesis and tumor invasiveness." (PMID 28929116, 2017). "Unexpectedly, the results of the present study showed that 3 kinds of cytokines (IL-5, IL-20, and IL-28A) correlate with metastatic potential without altering cell proliferation, which results in bladder cancer cell migration and invasion through MMP-2 and MMP-9 expression." (PMID 22962576, 2012).
Cerebral ischemia (210 papers, 2005 to 2026). Restriction of arterial blood supply to the brain associated with insufficient oxygenation to support the metabolic requirements of the tissue. "Considering that microglia are a significant source of MMP-9 after focal brain ischemia, and their association with blood vessels can contribute to vascular disintegration, we additionally explored microglia-vascular contacts in this context." (PMID 40964705, 2025). "The increase in MMP9 following cerebral ischemia has been associated with an expansion of the ischemic area and the development of cerebral edema." (PMID 37927954, 2023). "Scutellarin prevents blood–brain barrier damage caused by cerebral ischemia, by inhibiting iNOS expression and decreasing MMP-9 transcription and synthesis." (PMID 36678547, 2022). "MMP-9 is a gelatinase that degrades major components of the basal lamina, whose expression is upregulated after cerebral ischemia and has been associated with blood–brain disruption." (PMID 34685473, 2021). "During the inflammatory responses of brain ischemia and hypoxia, the white blood cells, microglia, and astrocytes can produce MMP-9, and the MMP-9 levels are closely associated with the severity of cerebral infarction." (PMID 34987460, 2021). "In cerebral ischemia, enhanced expression of matrix metalloproteinase-9 (MMP-9) is associated with various complications, including neuronal damage, apoptosis, and blood-brain barrier (BBB) disruption." (PMID 33162790, 2020). "We recently demonstrated that brain pericyte somata were associated with very early and localized MMP-9 activation along capillaries during cerebral ischemia, leading to focal blood-brain barrier disruption." (PMID 33505320, 2020). "During brain ischemia, aberrant nitric oxide levels can cause cellular injury through induction of nitrosative/oxidative stress and post-translational activation of matrix-metalloproteinase-9 (MMP-9)." (PMID 33505320, 2020). "In the early stages of cerebral ischemia (ranging from a few hours to a few days), MMP-9 damages the blood-brain barrier, causing leakage, leukocyte infiltration, cerebral edema, and even bleeding." (PMID 30245755, 2018). "Activation of MMP-9 following cerebral ischemia is closely associated with BBB leakage and microglial activation, and causes severe brain edema or hemorrhagic transformation." (PMID 30584250, 2018). "Increased expression levels of MMP-9 are associated in several pathological conditions such as neuronal cell death in glaucoma, cerebral ischemia, diabetic retinopathy, injured peripheral nerves, and retinal degeneration including RP." (PMID 27893855, 2016). "Consistently, in the case of cerebral ischemia, elevation in the level of MMP-9 via glycogen synthase kinase-3β suppression caused an increase in CXCR4 expression for subsequent mediating BMMSCs migration." (PMID 27130910, 2016). "MMP-9 is particularly critical during this process, as previous studies have demonstrated that BBB integrity is maintained after cerebral ischemia in MMP-9-deficient mice." (PMID 25177270, 2014). "Higher MMP-9 was observed in the presence of cerebral ischemia associated with cerebral vasospasm (p<0.05)." (PMID 23555845, 2013). "Evidence in human and animal models shows BBB disruption is associated with activation of matrix metalloproteinase-9 (MMP-9) after cerebral ischemia and inflammation." (PMID 23829879, 2013). "Expression and activation of MMP-9 following cerebral ischemia are closely associated with disruption of the blood–brain barrier (BBB), and cause severe brain edema or hemorrhagic transformation." (PMID 23972823, 2013). "Cerebral ischemia has been shown to induce activation of matrix metalloproteinases (MMPs), particularly MMP-9, which is associated with impairment of the neurovasculature, resulting in blood–brain barrier breakdown, hemorrhage and neurodegeneration." (PMID 22587708, 2012). "Evidence shows that MMP-9 is linked to increased cerebral ischemia." (PMID 39166055, 2024).
Cerebral ischemia (continued). "Besides, in a mouse model of permanent focal cerebral ischemia, this drug has beneficial effects on NVU because it prevents cerebral ischemia caused by glutamate excitotoxicity, decreases glial activation, and decreases MMP-9 secretion." (PMID 33670754, 2021). "Our data suggest that irisin can attenuate brain damage both morphologically and functionally and protect BBB from disruption after focal cerebral ischemia/reperfusion, which is highly associated with the inhibition of the expression and activity of MMP‐9 in the brain tissue." (PMID 31566928, 2019). "Many studies have confirmed that MMP-9 causes BBB damage in cerebral ischemia." (PMID 30618576, 2018). "We conclude that blockage of TRPV4 may inhibit brain edema in cerebral ischemia through inhibiting MMP-9 activation and the loss of tight junction protein." (PMID 25914628, 2015). "Interestingly, elevated levels of MMP-9 were not only associated with cerebral vasospasm in our study population but also with the presence of cerebral ischemia attributable to cerebral vasospasm." (PMID 23555845, 2013). "MMP-9 has been implicated in atherosclerotic plaque rupture, tissue damage after acute myocardial infarction, and breakdown of the blood-brain barrier and development of brain edema after cerebral ischemia and in other CNS conditions." (PMID 23185522, 2012). "In an experimental model of cerebral ischemia, systemic inflammation caused sustained disruption of the tight junction protein, claudin-5, and also exacerbated disruption of the basal lamina collagen-IV, and these alterations were associated with an increase in neutrophil-derived MMP-9." (PMID 25309322, 2014). "Matrix metalloproteinase-9 (MMP-9) plays a major role in cerebral ischemia as it breaks down the components of extracellular matrix, which maintains the tissue structure and integrity, making MMP-9 a potential target for therapeutic intervention." (PMID 42133657, 2026). "Following brief focal cerebral ischemia, oxidative stress triggers mmp9 to mediate the blood-brain barrier’s collapse." (PMID 40728995, 2025). "The protective effects of irisin against blood–brain barrier (BBB) dysfunction following focal cerebral ischemia/reperfusion in rats are accompanied by decreases in the expression and activity of matrix metalloproteinase-9 (MMP-9) in the cortex." (PMID 41373506, 2025). "Quercetin reduces blood-brain interference and condenses the quantity of MMP-9 in tests for cerebral ischemia, according to antioxidant analyses that are similar to those of green tea polyphenols." (PMID 40520194, 2025). "After knocking out the tissue inhibitor of metalloproteinases‐3 (TIMP‐3) in mice, it can reduce the expression of MMP3 and MMP9 and reduce the death of immature oligodendrocytes after cerebral ischemia." (PMID 40864831, 2025). "The expression and activity of matrix metalloproteinase-9 (MMP-9) are markedly upregulated within hours after cerebral ischemia, resulting in reduced endothelial tight junctions and ultimately BBB breakdown." (PMID 41322306, 2025). "MMP‐9 is critically involved in the initial phase of cerebral ischemia–reperfusion injury, exhibiting significant influence within the initial 24‐hour period." (PMID 38379112, 2024). "Salvianolic acid A has been shown to alleviate cerebral ischemia–reperfusion injury by inhibiting inflammation and apoptosis, promoting neurogenesis, and suppressing MMP-9 expression." (PMID 38600597, 2024). "It has been found that proteasome inhibition protects the BBB from cerebral ischemia by inhibiting neuroinflammation-mediated matrix metalloproteinase-9 (MMP-9) activation." (PMID 40190514, 2024). "The expression of tight junction proteins ZO-1 and occludin, matrix metalloproteinase MMP-2, and MMP-9 in cerebral cortex tissue of cerebral ischemia/reperfusion rats at 24 h were quantitatively detected by the Western blot technique." (PMID 38927572, 2024).